GPX8 (glutathione peroxidase 8 (putative))
Diseases named in the same sentence as GPX8 in open-access papers (continued):
Sharing a sentence is not in itself a finding about the gene and the disease.
tumor (18 papers, 2022 to 2026). "GPX8 was significantly upregulated in tumor tissue and was associated with a poor prognosis in STAD and COAD patients." (PMID 39833079, 2025). "Further studies are required to elucidate the precise mechanisms underlying the role of GPX8 in tumor immune infiltration." (PMID 39833079, 2025). "The TIMER database and TNMplot database were used to systematically evaluate the association of GPX8 with tumor-infiltrating lymphocytes in adenocarcinoma." (PMID 39833079, 2025). "In HCC, we discovered that GPX8 depletion was associated with a poor clinical prognosis and a more aggressive tumor malignant phenotype, and we created a signaling pathway diagram to help explain our findings." (PMID 38607517, 2024). "We found that the activation of GPX8 in the tumor microenvironment is associated with poorer survival outcomes and the development of an immunosuppressive environment." (PMID 38515109, 2024). "In our work, we assessed the association of GPX8 and tumor-infiltrating lymphocytes in adenocarcinoma carcinoma." (PMID 35712475, 2022). "Then, we used the TIMER database to find the association between GPX8 and tumor-infiltrating lymphocytes in the tumor microenvironment." (PMID 35712475, 2022). "The TIMER database and GSEA database were used to systematically evaluate the association of GPX8 and tumor-infiltrating lymphocytes in adenocarcinoma carcinoma." (PMID 35712475, 2022). "Meanwhile, the up-regulated expression of genes, including Maob, Sord, Steap3 and Gpx8 are associated with oxidative stress, illustrating that the produced ROS plays an important role in tumor growth inhibition." (PMID 36435848, 2022). "Collectively, these results indicate that genetic variants within the GPXs family may contribute to tumor formation and partly account for the association between GPX8 and aggressive tumor characteristics." (PMID 38515109, 2024). "Based on the median GPX8 expression level in the tumor tissues, we categorized the patients into 2 groups, a high GPX8 expression group and a low GPX8 expression group." (PMID 39833079, 2025). "Our analysis revealed a significantly higher GPX8 expression in tumor tissues compared to adjacent normal tissue in both STAD and COAD, and high expression was associated with reduced OS." (PMID 39833079, 2025). "Immunohistochemistry was conducted to assess GPX8 expression levels in tumor tissues and adjacent normal tissues from 50 patients with STAD and 50 patients with COAD." (PMID 39833079, 2025). "The study analyzed a cohort of patients, including GPX8 expression, immune infiltration, and survival rates, providing important insights into the potential mechanisms of GPX8 in regulating the tumor microenvironment and immune response." (PMID 39833079, 2025). "While it offers valuable insights, the precise mechanisms by which GPX8 influences Hsc70’s translocation and the broader implications for oxidative stress management within the tumor microenvironment are still yet to be fully elucidated." (PMID 38607517, 2024). "Regarding tumor microenvironment expression patterns, we observed a significant correlation between GPX8 and the infiltration of non-tumor cellular components." (PMID 38515109, 2024). "When GPX8 expression reduces, the expression of tumor stemness markers, such as KLF4, OCT4, and CD133 tend to increase." (PMID 38607517, 2024). "Sankey diagram showed that the tumor microenvironment properties in the high expression GPX8 group were predominantly C2 immune subtype and F subtype predominant." (PMID 38515109, 2024). "Considering that TCGA-LUAD patients have abundant information about the properties of the defined tumor microenvironment, we analyzed the correlation between GPX8 and the tumor microenvironment in the TCGA cohort." (PMID 38515109, 2024).
tumor (continued). "In conclusion, these results suggest that the tumor microenvironment with active GPX8 expression mainly exhibits immunosuppressive cell-enriched and fibroblast-enriched phenotypes as well as an active EMT program phenotype." (PMID 38515109, 2024). "Heatmaps showed the distribution of 29 known tumor microenvironmental signatures in relation to GPX8 expression." (PMID 38515109, 2024). "GPX8 expression at both mRNA and protein levels revealed significantly higher expression in tumor tissues compared to the normal group." (PMID 38515109, 2024). "The findings from this study suggest that GPX8 is downregulated in HCC patients, a trend that is associated with an increased risk of early tumor recurrence and lower chances of patient survival." (PMID 38607517, 2024). "Put together, these results showed that in vitro or in vivo, GPX8 knockdown promotes the tumor malignancy phenotype through the PI3K-AKT signaling pathway in an AKT-dependent manner." (PMID 38607517, 2024). "According to the scRNA-seq analysis, tumor cells and macrophages were shown to express GPX8 at high levels." (PMID 37795080, 2023). "Non-tumor HepaRG cells exhibited a much higher expression of GPX8 and a much lower expression of GPx7." (PMID 37189460, 2023). "At the single-cell RNA sequencing level, GPX8 appeared to facilitate cell contact between tumor cells and macrophages, potentially enhancing microglial migration." (PMID 37795080, 2023). "In this study, we analyze the expression of gpx1 to gpx8 genes for the eight known GPx isoforms in brain tissue from healthy control animals and tumor tissue from animals after transplacental ENU administration, also considering gender differences." (PMID 37761814, 2023). "In vivo xenograft experimentation also showed smaller tumor volumes and lower tumor weights from GPX8-KO than from WT." (PMID 36750850, 2023). "The data of the HPA database showed the different expression levels of GPX8 in normal or tumor tissue of the colon, kidney, lung, endometrium." (PMID 35402257, 2022). "NDRG2 expressed in astrocytes of the central nervous system is negatively correlated with gpx8, which is involved in cell proliferation and differentiation and generally considered as a tumor suppressor." (PMID 36052280, 2022). "GPX8 was highly expressed in the tumor tissues compared with the normal tissue adjacent to the tumor (NAT), and more GPX8‐high expressed tumors (55% vs. 34%) were observed in the metastasis group than that in the non‐metastasis group." (PMID 35978854, 2022). "Meanwhile, the expression of GPX8 was associated with the infiltration of CD8+ T cells, tumor-associated fibroblasts, plasma cells, macrophages, myeloid dendritic cells, neutrophils, and CD4+ T cells in the GBM microenvironment, but not with NK cells." (PMID 36061208, 2022). "To confirm the expression of GPX8 in primary tumors, we collected the tumor tissues and paracancerous ones from patients with GBM." (PMID 35402257, 2022). "Our work aimed to determine the possible involvement of glutathione peroxidases 4 and 8 (GPx4 and GPx8) in this specific tumor process." (PMID 35208621, 2022). "Collectively, our findings revealed that GPX8 plays a pivotal role in the immune infiltration of the GBM tumor microenvironment." (PMID 36061208, 2022). "While the findings suggest GPX8 may regulate the tumor microenvironment and immune response, the retrospective nature of the study and reliance on data from a single institution limit the generalizability of the findings." (PMID 39833079, 2025). "The in vivo downregulation of GPX8 could also promote the subcutaneous tumor-forming and migration ability of HCC cells." (PMID 38607517, 2024). "In vivo experiments were used to confirm the tumor-promoting effect of GPX8 knockdown, in addition to determining whether it is dependent on AKT phosphorylation or not." (PMID 38607517, 2024). "The downregulation of GPX8 could increase the expression of the tumor stemness markers KLF4, OCT4, and CD133." (PMID 38607517, 2024).
tumor (continued). "The expression differences of GPX8 between tumor and normal samples were examined." (PMID 37795080, 2023). "GPX8 knockout or downregulation substantially reduced lipid droplet levels (independent of lipid uptake), fatty acid de novo synthesis, triglyceride esterification in vitro, and tumor growth in vivo." (PMID 36750850, 2023). "Meanwhile, GPX8 mRNA expression was significantly correlated with monocyte marker CD14, dendritic-cell marker NRP1, natural killer cell marker B3GAT1, neutrophil marker CCR7, and tumor-associated fibroblast marker FAP." (PMID 36061208, 2022). "Furthermore, we confirmed the expression of GPX8 was higher in GBM tumor tissues than paracancerous ones." (PMID 35402257, 2022). "In addition, GPX8 was highly expressed in tumor tissues compared to the normal tissues both in the mRNA and protein levels (Xu2020_LUAD cohort and Gillette2020_LUAD cohort)." (PMID 35978854, 2022). "Next, the function of GPX8 in tumor growth was conducted in vitro and in vivo." (PMID 35978854, 2022). "Furthermore, the validation of GPX8 expression in more tumor samples needs to be further studied, as well as the relationship between GPX8 expression and the survival curve of patients with GBM." (PMID 35402257, 2022). "GPX8 was highly expressed in tumor tissues, predicting poor prognosis in LUAD patients." (PMID 35978854, 2022). "Furthermore, the expression level of GPX8 in tumor tissues with the late stage of LUAD was much higher than that in the early stage." (PMID 35978854, 2022). "In addition, GPX8 has also been found to promote tumor progression through multiple important pathways, such as Wnt and JAK/STAT3." (PMID 36061208, 2022). "In addition, to further clarify tumor immune function of GPX8, we then analyzed the correlation between GPX8 mRNA expression and levels of immune cell infiltration in GBM using the TIMER2.0 database." (PMID 36061208, 2022). "Moreover, GPX8 was highly expressed in the tumor tissues compared to the normal tissues, indicating that targeting GPX8 may provide therapeutic benefit with little side effect." (PMID 35978854, 2022). "Our data demonstrated that GPX8 was correlated with mRNA expression of immune markers of CD8+ T cells (CD8B), CD4+ T cells (CD4), T cells (CD3D), macrophages (CD68 and ARG1), neutrophils (ITGAM and CCR7), dendritic cells (NRP1), NK cells (B3GAT1), and tumor-associated fibroblasts (FAP)." (PMID 36061208, 2022). "The oncogenic components, namely, ALDH1B1, ALDH1L2, CHSY1, CSGALNACT2, and GPX8, were progressively upregulated in more aggressive tumors, while the tumor suppressor hubs FBP1 and HPGD were downregulated as tumor aggressiveness increased." (PMID 40626022, 2025). "We obtained tumor purity information of TCGA-LUAD patients from a previous study and performed correlation analysis with gene expression of GPX8." (PMID 38515109, 2024). "The expression of CDK1, ECT2, GJB2, GPR37, GPX2, and GPX8 gene was up-regulated in the tumor group (p < 0.001), whereas the expression of TLR4 was down-regulated in the tumor group (p < 0.001) when compared with those in the normal group." (PMID 37689745, 2023). "CDK1, ECT2, EZH2, GJB2, GPR37, GPX2, and GPX8 mRNA expression was up-regulated in the tumor group (p < 0.001), whereas GPX3, HYAL1, and TLR4 mRNA expression was down-regulated in the tumor group (p < 0.001) compared with those in the normal group." (PMID 37689745, 2023). "However, the tumor biological function of GPX8 remains unclear, especially in GBM." (PMID 36061208, 2022). "TUBA1C, which is positively correlated with GPX8, has been reported to be a prognostic marker in LGG and correlated with immune cell infiltration in the tumor microenvironment." (PMID 36052280, 2022). "The protein level of GPX8 in LUAD tissues microarray with 75 paired normal and tumor tissues was detected by immunohistochemical (IHC) staining." (PMID 35978854, 2022).
tumor (continued). "Our current study, based on single-cell sequencing data and comprehensive analysis of multiple independent bulk-RNA cohorts, has identified that GPX8 is expressed aberrantly in LUAD and is primarily found in CAFs, where it plays a key role in tumor progression." (PMID 38515109, 2024). "The results showed that GPX8 was negatively correlated with tumor purity (R=-0.295, P < 0.001), suggesting that GPX8 was mainly expressed in non-tumor cells." (PMID 38515109, 2024). "Similarly, in esophageal squamous carcinoma cells, GPX8 was found to induce the onset of autophagy and apoptosis by regulating the IRE1/JNK pathway in tumor cells." (PMID 38515109, 2024). "Together, these findings suggest that the interplay between GPX8 and CAFs significantly influences LUAD tumor progression, and GPX8+ CAFs could represent a novel therapeutic target for future CAF-directed treatments." (PMID 38515109, 2024). "Third, patients with new tumor events after primary therapies had higher GPX8 levels than those without them." (PMID 36750850, 2023). "Collectively, these results show that knockdown of GPX8 inhibits LUAD metastasis without tumor growth inhibition in vitro and in vivo." (PMID 35978854, 2022). "Statistical analysis did not reveal any significant differences in both the GPx4 and GPx8 groups with regard to the quantity of expression, age, gender, tumor grade, histotype or regional lymph node lesion." (PMID 35208621, 2022). "Furthermore, the UALCAN database data confirmed that the protein expression level of GPX8 in tumor tissues of COAD, KIRC and LUAD were higher than normal, and the higher expression of GPX8 was related to the late clinical stage." (PMID 35402257, 2022). "When we analyzed the ccRCC single-cell RNA sequencing data, NNMT expression was clearly higher in tumor cells than in other cell types but similar between the WT- and MT-VHL tumor cells (Unfortunately, GPX8 expression could not be analyzed, due to non-reliable detection in this particular dataset)." (PMID 36750850, 2023). "GPx4 and GPx8 probably do not play an important role in CRC pathogenesis, but antioxidants are discussed as dual actors in tumor development." (PMID 35208621, 2022). "Knockdown of GPX8 inhibited LUAD metastasis in vitro and in vivo, while it did not obviously affect tumor growth." (PMID 35978854, 2022).
GPX8 also shares sentences with these, for which no sentence is quoted: adenocarcinoma (2 papers); colon adenocarcinoma (2); stomach cancer (2); bladder cancer (1); Breast invasive carcinoma (1); cervical cancer (1); cholangiocarcinoma (1); head and neck squamous cell carcinoma (1); influenza (1); kidney cancer (1); Lung squamous cell carcinoma (1); Oral cancer (1); pulmonary fibrosis (1); rectal cancer (1); rectum adenocarcinoma (1); renal cell carcinoma (1); Renal cyst (1); thymus cancer (1); thyroid carcinoma (1); uterine corpus endometrial carcinoma (1).